FBXL13 (F-box and leucine rich repeat protein 13)
Description:
Substrate-recognition component of the SCF (SKP1-CUL1-F-box protein)-type E3 ubiquitin ligase complex. Component of the nexin-dynein regulatory complex (N-DRC), a key regulator of ciliary/flagellar motility which maintains the alignment and integrity of the distal axoneme and regulates microtubule sliding in motile axonemes. Specifically targets CEP192 isoform 3 for ubiquitin-mediated proteolysis and thereby acts as a regulator of microtubule nucleation activity.
Synonyms: DRC6; FBL13; MGC21636; CFAP169
Tractability: No criterion of Open Targets' tractability assessment is met for any kind of drug.
Gene: Protein-coding gene on chromosome 7 (102,811,189 to 103,075,400, reverse strand). Ensembl gene ENSG00000161040.
Subcellular location: Cytoplasm, cytoskeleton, flagellum axoneme; Cytoplasm, cytoskeleton, microtubule organizing center, centrosome
Pathways (Reactome):
Immune System: Antigen processing: Ubiquitination & Proteasome degradation
Metabolism of proteins: Neddylation
Gene Ontology:
Biological process: cilium movement; flagellated sperm motility; regulation of centrosome duplication; SCF-dependent proteasomal ubiquitin-dependent protein catabolic process
Cellular component: axonemal nexin link; axoneme; cytosol; centrosome
Genetic constraint (gnomAD): Loss-of-function variants: 33 observed, 50.1 expected, observed/expected ratio (o/e) 0.66, 90% interval 0.5 to 0.88. The upper end of that interval is the gene's LOEUF score, 0.88, which puts it in group 3 of 6, group 1 being the genes least tolerant of losing a copy. Missense variants: 590 observed, 670.82 expected, observed/expected ratio (o/e) 0.88, 90% interval 0.82 to 0.94. Synonymous variants: 200 observed, 237.12 expected, observed/expected ratio (o/e) 0.84, 90% interval 0.75 to 0.95.
Homologues: Orthologues: chimpanzee FBXL13 (88% identical), macaque FBXL13 (80% identical), dog FBXL13 (77% identical), rabbit FBXL13 (74% identical), rat Fbxl13 (71% identical), pig FBXL13 (69% identical), guinea pig FBXL13 (68% identical), mouse Fbxl13 (64% identical), tropical clawed frog fbxl13 (45% identical), zebrafish fbxl13 (28% identical), Drosophila melanogaster CG9003 (14% identical), Drosophila melanogaster CG8272 (13% identical), and 24 more. Paralogues in human: FBXL2 (14% identical), FBXL20 (13% identical), FBXL5 (13% identical), FBXL7 (12% identical), FBXL14 (12% identical), FBXL6 (11% identical), SKP2 (11% identical), FBXL17 (11% identical), FBXL3 (11% identical), FBXL18 (10% identical), FBXL4 (10% identical), FBXL19 (10% identical), and 3 more.
Diseases named in the same sentence as FBXL13 in open-access papers:
FBXL13 is named in the same sentence as 3 diseases in open-access papers, as found by Europe PMC text mining. Sharing a sentence is not in itself a finding about the gene and the disease. The quoted sentences say what the papers report.
bipolar disorder (1 paper, 2017). A disorder of the brain that causes unusual shifts in mood, energy, activity levels and the ability to carry out day-to-day tasks. "FBXL13 functions in the maturation of human dendritic cells which are key regulators in the immune system and show mild aberrancies in bipolar disorder that can be fully restored to even activation after in vivo lithium treatment." (PMID 29257106, 2017).
Obesity (1 paper, 2019). Accumulation of substantial excess body fat. "MiR-197-3p and miR-23b-3p were downregulated in T2D+ patients with obesity; thus we could expect increased expression of their targets, TNFAIP6, RUNX2, and FBXL13, in these patients." (PMID 31866945, 2019).
FBXL13 also shares sentences with these, for which no sentence is quoted: tumours (1 paper).